TIPE2 (TNF alpha induced protein 8 like 2)
Diseases named in the same sentence as TIPE2 in open-access papers (continued):
Sharing a sentence is not in itself a finding about the gene and the disease.
lung carcinoma (continued). "Therefore, we determined the molecular targets which are involved in the TIPE2-mediated tumorigenic effect in tobacco facilitated lung cancer." (PMID 31817720, 2019). "In the present study, we determined the role of TIPE2 in lung cancer." (PMID 31817720, 2019). "Initially, we analyzed the expression of TIPE2 in human lung cancer tissues." (PMID 31817720, 2019). "In addition, knockout of TIPE2 reduced the proliferation, survival, invasion, and migration of human lung cancer cells." (PMID 31817720, 2019). "Notably, in TIPE2 knockout cells, downregulation of LC-3B was observed, which can be presumed to aid in reducing proliferation and survival of lung cancer cells." (PMID 31817720, 2019). "Therefore, to determine the effect of TIPE2 on the viability and survival of human lung cancer cells, first, knockout of TIPE2 was done." (PMID 31817720, 2019). "This study shows TIPE2 to be involved in the positive regulation of lung cancer." (PMID 31817720, 2019). "The arrest in the S phase as a result of TIPE2 knockout might induce apoptosis of lung cancer cells." (PMID 31817720, 2019). "Besides, we found that knockout of TIPE2 led to the increased cell number in the S phase of the cell cycle in lung cancer cells." (PMID 31817720, 2019). "In addition, phosphatase and tensin homolog (PTEN), a lipid and protein phosphatase, was found to be upregulated in TIPE2 knockout lung cancer cells." (PMID 31817720, 2019). "MTT assay and colony formation assay analysis showed reduction of cell viability and fewer colonies observed in H446/TIPE2 respectively, compared with H446/Control and H446/Null cells, which indicated TIPE2 could inhibit lung cancer cell growth." (PMID 25946186, 2015). "In our present study, we demonstrated the state of TIPE2 expression in lung cancer." (PMID 25946186, 2015). "Taken together, TIPE2 functions as a tumor suppressor to promote lung cancer cell apoptosis." (PMID 25946186, 2015). "Combined with these results, we speculate that TIPE2 promotes lung cancer cell apoptosis through activation of P38 MAPK, which triggers the over-expression of caspase-3 and caspase-9." (PMID 25946186, 2015). "In present study, we provide evidences firstly indicate that TIPE2 suppresses the growth and promotes apoptosis of lung cancer through regulating the Bcl-2/Bax balance and then leads to the activation of caspase-3 and caspase-9 possibly via affecting P38 and Akt pathway." (PMID 25946186, 2015). "So, our results provide a lot of evidence that TIPE2 promotes lung cancer apoptosis." (PMID 25946186, 2015). "Thus, TIPE2 is found to be involved in the modulation of lung cancer cells’ migration as well." (PMID 31817720, 2019). "Besides, the role of TIPE2 in tobacco-promoted lung cancer was also determined." (PMID 31817720, 2019). "Hence, we identified those molecular targets through which TIPE2 might mediate its tumorigenic effect in tobacco-facilitated lung cancer." (PMID 31817720, 2019). "Thus, TIPE2 is observed to activate the Akt/mTOR signaling pathway, which might contribute to lung cancer pathogenesis." (PMID 31817720, 2019). "Additionally, a study on HCC showed NF-κB to be involved in TIPE2 mediated lung cancer." (PMID 31817720, 2019). "However, some reports showed TIPE2 could inhibit the invasion of various cancer cells, including prostate cancer and lung cancer cells." (PMID 28851386, 2017). "Taken together, TIPE2 promoted lung cancer cell apoptosis through affecting apoptosis-related molecules caspase-3, caspase-9, Bcl-2 and Bax, possibly via regulating P38 and Akt pathways, indicating that TIPE2 might be a novel marker for lung cancer diagnosis and therapy." (PMID 25946186, 2015). "Furthermore, this study preliminarily interpreted the biological function of TIPE2 in lung cancer." (PMID 25946186, 2015). "However, the TIPE2 expression pattern in lung cancer is unclear so far." (PMID 25946186, 2015).
lung carcinoma (continued). "Therefore, the forced expression of human TIPE2 may be a new strategy for treatment of lung cancer." (PMID 25946186, 2015). "However, the relationship between TIPE2 and lung cancer is unknown so far." (PMID 25946186, 2015). "The difference of TIPE2 between the subtypes of lung cancer and adjacent non-tumor lung tissues respectively." (PMID 25946186, 2015). "In addition, our results showed for the first time that TIPE2 is involved in the positive regulation of nicotine-, NNK-, NNN-, and BaP-promoted proliferation, survival, and migration of lung cancer cells through modulation of NF-κB and NF-κB-regulated gene products." (PMID 31817720, 2019). "In addition, overexpression of TIPE2 inhibited the proliferation, colony formation, invasion, and the expression of Bcl-XL and N-cadherin, involved in regulating apoptosis and EMT phenomenon in lung cancer cells." (PMID 31817720, 2019). "Interestingly, we found Ki-67 expression had no alteration after TIPE2 over-expression, which indicated that TIPE2 inhibited lung cancer growth attributing to promotion of cell apoptosis." (PMID 25946186, 2015). "In lung cancer stroma, no stain of TIPE2 was found in fibroblasts cells, but strong staining could be found in inflammatory cells such as plasmocytes and macrophagocytes." (PMID 25946186, 2015).
atherosclerosis (7 papers, 2018 to 2024). A disease characterized by the build-up of fatty material and calcium deposition in the arterial wall resulting in partial or complete occlusion of the arterial lumen. "TIPE2 can treat atherosclerosis by inhibiting the NF-κB signaling pathway to decrease the inflammatory response of macrophages." (PMID 36983674, 2023). "TIPE2 suppresses atherosclerosis by exerting a protective effect on oxidized low-density lipoprotein-induced macrophages through the inhibition of the PI3K/Akt and NF-κB signaling pathways." (PMID 34446024, 2021). "TIPE and TIPE2, the regulators of immunity, have been demonstrated to protect against inflammatory diseases such as atherosclerosis, colitis, and rheumatoid arthritis." (PMID 30274259, 2018). "In addition, the aberrant presence of TIPE2 plays an important physiological role in the onset, development, and progression of diabetic nephropathy, atherosclerosis, stroke, and carcinoma." (PMID 33815396, 2021). "Further, TIPE2 displayed its atheroprotective role through modulation of phenotypic switching of vascular smooth muscle cells (VSMCs), which plays a vital role in the development of atherosclerosis in response to ox-LDL stimuli." (PMID 30274259, 2018). "TIPE2 can accelerate the differentiation of M2 macrophages by activating the PI3K signaling pathway, significantly reduce the expression of TNF-α, IL-6, and MCP-1, and play a protective role in atherosclerosis." (PMID 37069964, 2023).
chronic hepatitis B (7 papers, 2016 to 2019). "In conclusion, TIPE2 might be associated to the immune clearance of patients with chronic hepatitis B." (PMID 28390195, 2017). "In summary, TIPE2 might be associated with immune clearance of patients with chronic hepatitis B. Furthermore, the optional cut off values of 2.02 and 1.59 for TIPE2 mRNA as biomarker have strong power in identifying CHB patients with IC and ENH phases from patients with IT and LR phases." (PMID 28390195, 2017). "In the present study, we demonstrated that the median levels of TIPE2 mRNA in chronic hepatitis B were significantly higher compared with those in healthy controls." (PMID 31661000, 2019). "Xi and colleagues reported that patients with chronic hepatitis B exhibited remarkably decreased TIPE2 expression in their peripheral blood mononuclear cells (PBMCs) compared to healthy individuals." (PMID 30274259, 2018). "A decreased expression of TIPE2 has been observed in the PBMCs of patients with chronic hepatitis B infection and patients with primary biliary sclerosis." (PMID 30586922, 2018). "This present study was to assess the expression of TIPE2 in the natural history of chronic hepatitis B with different immune phases." (PMID 28390195, 2017). "Intriguingly, recent studies have reported that TIPE2 expression was decreased in the peripheral blood mononuclear cells (PBMCs) of patients with chronic hepatitis B and in HBV-related HCC tumor tissue." (PMID 27696294, 2016). "TIPE2 expression also modulates chronic hepatitis B virus infection." (PMID 30586922, 2018). "TIPE2 also expresses in autoimmune hepatitis and chronic hepatitis B." (PMID 30157801, 2018). "However, the potential role of TIPE2 in the various immune phases of chronic hepatitis B remains still unknown." (PMID 28390195, 2017). "Here, we first determined the mRNA expression levels of TIPE2, IL-6, IL-10, TNF-α, and IFN-γ in peripheral blood mononuclear cells from 205 naïve treated patients with chronic hepatitis B, as well as 15 healthy controls." (PMID 28390195, 2017). "Therefore, TIPE2 might participate in the immune phases of patients with chronic hepatitis B." (PMID 28390195, 2017). "Further, in chronic hepatitis B (CHB) patients, TIPE2 mRNA level in immune clearance phases was notably more compared to the immune tolerance phase, indicating that TIPE2 might be involved in immune clearance of patients with CHB." (PMID 30274259, 2018). "Tumor necrosis factor-α-induced protein 8-like 2 (TIPE2) is a newly negative immune regulator but its role in different immune phases of patients with chronic hepatitis B (CHB) is unknown." (PMID 28390195, 2017).
colon cancer (7 papers, 2016 to 2025). "Present papers published on Tipe2 and colon cancer suggest Tipe2 a tumor suppressor but very few experiments to verify, especially no AOM/DSS CRC model." (PMID 34702807, 2021). "TIPE2 was up-regulated in the cytoplasm of colon cancer tissues and HT-20 colon cancer cells by inhibiting caspase-8 activity." (PMID 33817189, 2019). "A 2014 study was conducted to better understand the mechanism of TIPE2 via caspase 8 in colon cancer patients, and the study discovered that TIPE2 was dominantly expressed in colon cancer tissues and its expression was linked to lymph node distant metastasis and the Dukes stage of CRC." (PMID 40558596, 2025). "Research on colon cancer has shown that the level of TIPE2 in colon cancer tissues is significantly upregulated compared to adjacent normal tissues and that TIPE2 participates in the development of colon cancer by binding caspase 8, thereby inhibiting the TLR4 inflammatory pathway." (PMID 33850476, 2021). "TIPE2 expression was more pronounced in colon cancer tissues, but downregulated in HCC." (PMID 29108244, 2017). "The increased expression of TIPE2 in NSCLC tumor tissues made us doubt that TIPE2 may promote the development of NSCLC as that in colon cancer, different from that in HCC, where it acts as a tumor suppressor." (PMID 27556698, 2016).
experimental autoimmune encephalomyelitis (6 papers, 2012 to 2026). An autoimmune demyelinating disease of the central nervous system that is produced experimentally in animals by the injection of homogenized brain or spinal cord in Freund's adjuvant. "Spinal cord slices from TIPE2 knockout mice demonstrated decreased leukocyte infiltration in the experimental autoimmune encephalomyelitis model." (PMID 41563279, 2026). "Tumor necrosis factor-α induced protein-8-like 2 (TNFAIP8L2 or TIPE2) belongs to TNFAIP8 family and was identified to be over-expressed in mice with EAE (Experimental Autoimmune Encephalomyelitis)." (PMID 28122045, 2017). "Tumor necrosis factor-α induced protein 8-like 2 (TIPE2), a member of the TNFAIP8 family, was originally identified as a gene abnormally expressed in the inflamed spinal cord of mice with experimental autoimmune encephalomyelitis." (PMID 22666399, 2012). "To determine the roles of TIPE2 and TNFAIP8 in experimental autoimmune encephalomyelitis (EAE), an animal model for MS, we immunized WT, Tipe2–/–, Tnfaip8–/–, and Tipe2–/–Tnfaip8–/–DKO mice with myelin oligodendrocyte glycoprotein (MOG) peptide 35–55, and monitored daily for clinical signs of EAE." (PMID 32313148, 2020).
glioma (6 papers, 2018 to 2022). A benign or malignant brain and spinal cord tumor that arises from glial cells (astrocytes, oligodendrocytes, ependymal cells). "For example, TIPE2 inhibits hypoxia-induced activation of the Wnt/β-catenin pathway in glioma." (PMID 35388275, 2022). "Overexpression of TIPE2 prevents hypoxia-induced expression of β-catenin, cyclin D1, and c-myc in human glioma cells, suggesting that TIPE2 overexpression inhibits hypoxia-induced activation of the Wnt/β-catenin pathway and EMT in glioma cells." (PMID 35054779, 2022). "In addition, overexpression of TIPE2 led to the inhibition of hypoxia-induced migration as well as invasion and EMT in glioma cells." (PMID 31817720, 2019).
prostate carcinoma (6 papers, 2017 to 2021). A carcinoma that arises from epithelial cells of the prostate gland. "TIPE2 suppresses the proliferation, migration, and invasion of prostate cancer cells by inhibiting the PI3K/Akt signaling pathway." (PMID 34446024, 2021). "In prostate cancer cells, upregulation of TIPE2 inhibited the migration, invasion, and EMT through blockage of the PI3K/Akt signaling." (PMID 31817720, 2019). "The involvement of Akt in TIPE2-mediated carcinogenesis was also reported in the case of gastric and prostate cancers." (PMID 31817720, 2019). "In addition, TIPE2 overexpression led to decreased migration, invasion, and EMT in prostate cancer cells through PI3K/Akt inhibition." (PMID 31817720, 2019).
autoimmune disease (5 papers, 2016 to 2023). A disorder resulting from loss of function or tissue destruction of an organ or multiple organs, arising from humoral or cellular immune responses of the individual to their own tissue constituents. "TIPE2 has been reported to be aberrantly expressed in patients with various infectious and autoimmune diseases and is a key molecule in the prevention of inflammatory diseases." (PMID 37069964, 2023). "The novel mechanism discovery of TIPE2 in antiviral immunity provides new insights to avoid the toxic side effects of IFNs and crippling autoimmune diseases." (PMID 33815396, 2021). "Contradictory results have been reported when investigating the role of TIPE2 during the development of different types of autoimmune diseases." (PMID 31616442, 2019). "In order to determine the roles of TIPE2 in the pathogenesis of different types of autoimmune diseases, we established IMQ-induced psoriasis model and EAU model in wild-type and TIPE2-deficient mice in the C57BL/6 background." (PMID 31616442, 2019). "As a negative regulator of T cells and macrophages, TIPE2 can inhibit inflammation in autoimmune diseases." (PMID 29152095, 2017). "Using IMQ-induced psoriasis model and EAU model, our current study revealed that TIPE2 may either promote or suppress autoimmunity, depending on the specific inflammatory microenvironment in different types of autoimmune diseases." (PMID 31616442, 2019). "Taken together, these results indicate that TIPE2 may either promote or suppress autoimmunity depending on the specific inflammatory microenvironment in different types of autoimmune diseases." (PMID 31616442, 2019). "Since TIPE2 is a negative regulator of immune response, it may play important roles during the pathogenesis of autoimmune disease." (PMID 31616442, 2019). "However, studies on the role of TIPE2 during the development of autoimmune diseases have generated contradictory results." (PMID 31616442, 2019). "We speculate that TIPE2 may play both anti-inflammatory and pro-inflammatory roles during the development of autoimmune diseases." (PMID 31616442, 2019). "However, it still remains a question why TIPE2-deficient T cells were defective in migration to the site of inflammation in one particular autoimmune disease but not in another?" (PMID 31616442, 2019). "Thus, the role of TIPE2 during the development of autoimmune diseases remains elusive." (PMID 31616442, 2019). "Thus, depending on the specific inflammatory microenviroment in different types of autoimmune disease, TIPE2-deficiency may or may not affect the accumulation of T cells in the local inflammatory site." (PMID 31616442, 2019). "Although it has been reported that TIPE2 is a negative immune regulator, the exact role of TIPE2 during the development of autoimmune disease remains elusive." (PMID 31616442, 2019).
colorectal cancer (5 papers, 2018 to 2025). A primary or metastatic malignant neoplasm that affects the colon or rectum. "Our work reveals that Tipe2 might have dual function by regulating senescence: overexpression in tumor cells inhibits tumor cell proliferation and survival, while endogenous Tipe2-deficiency suppresses colitis-associated colorectal cancer (CRC) initiation." (PMID 34702807, 2021). "However, increased TIPE2 expression was also observed in some specific tumors including colorectal cancer (CRC), non-small cell lung cancer (NSCLC) and skin squamous cancer." (PMID 30186591, 2018).
Hepatitis (5 papers, 2017 to 2022). Inflammation of the liver. "In hepatitis mice, TIPE2 overexpression and TIPE2 knockdown alleviated and exacerbated steatosis and inflammation, respectively, and the expression level of TIPE2 was negatively correlated with TAK1 which is a downstream molecule of TLR." (PMID 35572554, 2022). "Taken together, TIPE2 possesses a strong correlation with the infection with hepatitis virus, and hence it can used as a target to develop strategies for the management of hepatitis-infected patients." (PMID 30274259, 2018). "It has been reported that TIPE2, a regulator of immune receptor signaling, can control HBV-induced hepatitis." (PMID 30274259, 2018). "Moreover, the TIPE2 mRNA level in immune clearance (IC) phases was significantly higher than that in immune tolerance (IT) phase; whereas TIPE2 mRNA in HBeAg negative hepatitis (ENH) was obviously higher than low replication (LR) phase." (PMID 28390195, 2017). "Interestingly, we reported that TIPE2 in immune clearance phases was higher than that in the immune tolerance phase, whereas TIPE2 in HBeAg-negative hepatitis was higher than that in the low replication phase, indicating that TIPE2 might contribute to the immune clearance of CHB patients." (PMID 31661000, 2019).
renal cell carcinoma (5 papers, 2013 to 2018). "The aim of the present study was to determine whether TIPE2 is associated with renal cell carcinoma (RCC) progression." (PMID 24137373, 2013). "TIPE2 suppresses TLR4-mediated development of colon cancer by inhibiting caspase-8 activity, while its expression is positively correlated with TNM staging in renal cell carcinoma (RCC) patients." (PMID 25946186, 2015). "On the other hand, it has been reported that TIPE2 expression is up-regulated in glomeruli from streptozotocin (STZ)-induced diabetic rats and renal biopsies of patients with diabetes, and PBMCs of chronic rejection patients, as well as renal cell carcinoma tissues, Non-Hodgkin’s Lymphoma." (PMID 28851386, 2017).
diabetic nephropathy (4 papers, 2012 to 2021). "In humans, the abnormal expression of TIPE2 was associated with systemic autoimmunity, diabetic nephropathy, and hepatitis B." (PMID 22666399, 2012). "Moreover, the expression of TNFAIP8 and TIPE2 is associated with diabetic nephropathy in glomeruli from streptozotocin (STZ)-induced diabetic rats, and renal biopsies of diabetic patients in vivo." (PMID 31723944, 2019). "The study further revealed that TNFAIP8, and not TIPE2 expression, is upregulated in response to high glucose in mesangial cells which leads to increased cell proliferation and up-regulation of NADPH oxidase-mediated signaling pathway, suggesting that TNFAIP8 modulates diabetic nephropathy." (PMID 31723944, 2019).